IL6 (interleukin 6)
Diseases named in the same sentence as IL6 in open-access papers (continued):
Sharing a sentence is not in itself a finding about the gene and the disease.
depression (continued). "In patients receiving hemodialysis, IL-6 is positively correlated with depression scores and malnutrition but negatively correlated with serum albumin concentrations." (PMID 37763079, 2023). "Nevertheless, we found those in severe depression before surgical treatment (10 patients) showed a decrease in the serum IL-6 level with marginal significance (3.30 pg/mL vs. 1.94 pg/mL, p = 0.047)." (PMID 37324195, 2023). "An increase of IL6, IL-1, IL-17, and TNFα in peripheral blood related to anxiety and depression compared to healthy controls." (PMID 37916198, 2023). "IL-6 change from baseline to D7 was positively correlated to anxiety (P=0.004) and depression (P=0.027) at discharge." (PMID 37878890, 2023). "Studies have revealed that individuals facing anxiety and depression often show increased plasma levels of inflammatory markers, such as tumor necrosis factor and interleukin-6 (IL-6)." (PMID 37809229, 2023). "Reports of animal studies and clinical trials indicate that among pro-inflammatory cytokines, IL-6 plays a unique role in the pathophysiology and somatic consequences of depression, and also mediate the effects of treatment of depressive disorder." (PMID 37365247, 2023). "Further evaluation of mental status revealed that patients with ENS with severe depression had higher serum IL-6 levels than others (p = 0.042)." (PMID 37324195, 2023). "Our study comprising a cohort of women with prenatal depression and anxiety showed higher concentrations of inflammatory biomarkers, predominantly IL-6, in those with more elevated depression and anxiety, assessed using a variety of mood scales." (PMID 37107316, 2023). "The study showed a bidirectional relationship between depression and sleep disorders, and a significant effect of depression and sleep disorders on IL-6 and IL-1β." (PMID 37509542, 2023). "Multiple meta-analyses showed that there were differences in pro-inflammatory cytokines between patients with severe depression and the control group, including IL-6, TNF-α, IL-1β, and CRP." (PMID 36846218, 2023). "The results showed that with the increase in interleukin-6 (after adjusting for age and gender), psychological problems (depression, anxiety, and stress) increase significantly (p < 0.05)." (PMID 37692307, 2023). "Depression occurs with disorders in inflammatory factors (e.g., IL-6), monoamine neurotransmitters (e.g., DA, NE, and 5-HT), and the function of the HPA axis." (PMID 37239191, 2023). "The current study investigated the relationship between IL-6 levels, amygdala emotional reactivity, and depression/anxiety, considering gene-psychosocial stressor interactions in nonclinical participants with various levels of depression/anxiety." (PMID 37324818, 2023). "In this study we found ENS patients with a higher preoperative serum IL-6 level related to a severe status of depression and would need timely management." (PMID 37324195, 2023). "Growing evidence indicate that elevated concentrations of inflammatory markers are associated with depression and anxiety, including C-reactive protein (CRP), interleukin 6 (IL-6), and other inflammatory markers." (PMID 37344456, 2023). "In their study, Lactobacillus was linked to depressive symptom reduction in human subjects, thereby suggesting a higher IL‐6 concentration in patients with BD can reduce depression." (PMID 37127945, 2023). "For instance, a meta-analysis, including a series of clinical data, showed a correlation between depression and inflammation among children, adolescents, and adults, such as the elevated levels of C-reactive protein and interleukin-6 (IL-6)." (PMID 36973813, 2023). "The present results indicated that CLM dramatically decreased the levels of TNF-α and IL-6 in the peripheral blood of patients with depression compared to antidepressant treatment groups." (PMID 37808199, 2023).
depression (continued). "A meta-analysis notes that serum sIL-2R, TNF-α, and IL-6 levels are significantly higher in patients with major depression than in healthy controls." (PMID 38084332, 2023). "Enhanced IL-6 activity in severe depression leads to hypotransferrinemia and hyperactivity of the HPA axis." (PMID 37762207, 2023). "Patients with SSRI-resistant depression have significantly higher production of the peripheral pro-inflammatory cytokines IL-6 and TNF-α compared to normal controls." (PMID 37700748, 2023). "Depressive symptoms and major depression were associated with elevated levels of inflammatory biomarkers such as C-reactive protein (CRP), interleukin (IL)-1, IL-6, tumor necrosis factor-alpha (TNF-α) and monocyte chemoattractant protein-1 (MCP-1)." (PMID 36915045, 2023). "After controlling for all covariates, we found that the moderately severe depression group had increased IL-6 (p = 0.003), IL-8 (p = 0.001), and IL-18 (p = 0.023) levels but decreased IFN-γ (p = 0.003) levels." (PMID 37637801, 2023). "Previous work investigating the causal role of CRP, interleukin-6 (IL-6, major moderator of CRP), BMI and specific symptom dimensions of depression (sleep, appetite, suicidality) used LD score regression and a range of two-sample MR analyses." (PMID 37710313, 2023). "Interleukin-6 (IL-6) is a potent biomarker for depression, as its elevated plasma levels in patients with clinical depression have been confirmed by a range of studies." (PMID 37510364, 2023). "For example, clinical depression is accompanied by increased levels of interleukin (IL)-1β, IL-6, IL-8, IL-17, IFN-γ, and TNF-α." (PMID 37509005, 2023). "Older adult T2DM patients with depression have significantly elevated levels of C-reactive protein, interleukin-6 and tumor cytokines, which also contribute to frailty." (PMID 38089021, 2023). "Laboratory results, including neutrophil lymphocyte ratio (NLR) upon admission, higher interleukin-6 (IL-6), and higher C-reactive protein (CRP), were associated with depression." (PMID 37027455, 2023). "Celecoxib treatment only improved peripheral IL-6 levels in depression and TNF-alpha levels in mania, but these are only single clinical studies on these markers." (PMID 37240605, 2023). "Some studies have reported increased interleukin-1β (IL-1β) and interleukin-6 (IL-6) and decreased IL-4 and IL-10 in patients with depression." (PMID 37139495, 2023). "Conversely, other studies have suggested that ECT has anti-inflammatory effects, and researchers performing ECT in patients with depression found reduced plasma levels of pro-inflammatory factors IL-6 and TNF-α and increased hippocampal volume." (PMID 36624089, 2023). "Meanwhile, patients with depressive episodes showed only increased IL-6 levels, and those in remission—only IL-4." (PMID 37662097, 2023). "The prevalence and severity of depression were significantly associated with D-dimer, CRP, ferritin, PCT, and Interleukin-6 (p<0.05)." (PMID 37621784, 2023). "Some clinical studies have reported increased levels of inflammatory cytokines and neutrophils in the blood of patients with major depression, and higher levels of interleukin 6 in the blood of drug-resistant patients." (PMID 37275977, 2023). "ROC curve analysis showed an optimal cut-off value of 1.985 pg/mL for preoperative serum IL-6 level to assess preoperative severe depression status (p = 0.049)." (PMID 37324195, 2023). "Meta-analyses have found increased C-reactive protein (CRP) and interleukin-6 (IL-6) in CVD patients, both of which are associated with higher risk of depression." (PMID 37009113, 2023). "Major depressive disorder (MDD) has been linked to inflammation, including significant increases in chemokines and cytokines including IL-1α, IL-1β, and IL-6." (PMID 37239169, 2023).
depression (continued). "A meta-analysis investigating the impact of the phase of depression found IL-6 levels in blood to be increased only in the acute phase of illness and among patients with chronic depression (based on 18 and 12 studies, respectively)." (PMID 37016363, 2023). "This implies that patients with ENS were more likely to experience severe depression when they had a preoperative IL-6 level > 1.985 pg/mL, with 69.2% sensitivity and 77.3% specificity." (PMID 37324195, 2023). "IL-6 is a proinflammatory cytokine that is increased by stress and involved in the development of depression." (PMID 37238588, 2023). "The evaluation of 292 individuals with major depression treated with fluoxetine for at least 6 weeks showed decreased levels of IL-1β, IL-6, or TNF-α at the end of the antidepressant treatment." (PMID 37242611, 2023). "It has also been found that quercetin, kaempferol, and aloe emodin in Xiaoyao Powder can reduce the expression of inflammatory cytokines by acting on targets likes IL-4 and IL-6 to treat depression." (PMID 37694120, 2023). "IL-6, a type of pro-inflammatory cell, is involved in the pathophysiology of major depressive disorder in the brain." (PMID 36737433, 2023). "Genotyping in patients with heart failure and comorbid depression revealed that genetic variants implicated in anxious behaviour (NPSR1) as well as inflammation (C-reactive protein (CRP), interleukin 6 (IL-6)) modify the risk of progression and mortality." (PMID 36959471, 2023). "Persistent elevation of pro-inflammatory markers, such as C-reactive protein (CRP), IL-6, and IL-1 in depression can promote the development and progression of atherosclerosis, a condition characterized by the buildup of fatty plaques in the arterial walls." (PMID 37599890, 2023). "Secondary outcomes to be assessed are the severity of co-morbid depression and anxiety symptoms; the serum levels of IL-1β, IL-6 and TNF-α; changes in ERP and fecal microbiota content." (PMID 38051740, 2023). "Vitamin D also can modulate proinflammatory cytokines (e.g., IL-6 and TNF-α), which are essential in systemic inflammation associated with depression and suicide." (PMID 37049606, 2023). "Childhood traumatic events are recognized risk factors for depression and other mental illnesses and are associated with elevated levels of inflammatory markers such as CRP or IL-6." (PMID 37700748, 2023). "Previous studies have shown that patients with depression had higher plasma levels of interleukin-6 compared to healthy controls." (PMID 37096248, 2023). "Among those positively associated with depression are C-reactive protein, IL-6 and TNF-α while markers negatively associated with depression include KYNA, KYNA/3HK ratio, KYNA/QUIN ratio and BDNF." (PMID 37457896, 2023). "The discovery that Th17 cells are involved in depression evolves from the classic theory that Th17 cells produce inflammatory cytokines IL-17A and IL-6, which is required for differentiation, and contribute to depression onset and maintenance." (PMID 36911710, 2023). "Levels of proinflammatory cytokines in peripheral blood were shown to be significantly increased in patients with major depressive disorder, such as IL-6, TNF-α and IL-1β." (PMID 37808199, 2023). "Simvastatin (20 mg/kg) has been shown in animal tests to diminish depression-like behaviour by lowering hippocampal inflammatory cytokines such as TNFA, IL1B and IL6, hence alleviating lipopolysaccharide-mediated depression and inflammation induced stress." (PMID 36602642, 2023). "Psychological stress plays a major role in depression, and interleukin-6 (IL-6) is elevated during depression and psychological stress." (PMID 37238588, 2023). "IL-6 triggers the JAK/STAT3 signaling cascade and modulates activation of the HPA axis in depression; thus, increasing IL-6 levels contributes to depression." (PMID 36648973, 2023). "Elevated levels of IL-1β and IL-6 are related to the severity of depression throughout the prenatal and postnatal periods." (PMID 37239199, 2023).
depression (continued). "Given its multisystem involvement, IL-6 has been previously suggested to play a large role in the pathophysiology of depression." (PMID 37928924, 2023). "Recent studies demonstrated increased levels of many pro-inflammatory cytokines, including interleukins (IL), such as IL-6, in individuals suffering from depression." (PMID 37840785, 2023). "Studies including patients with treatment-resistant depression showed that pro-inflammatory cytokines (mainly IL-6) decreased 4 h after a single intravenous injection of ketamine." (PMID 36769799, 2023). "Because there are reports that dysregulation of the dopamine system is involved in the pathophysiology of depression, in this study we investigated how IL-6 affects dopaminergic neuronal cells (LUHMES), astrocytes, and microglia." (PMID 37238588, 2023). "The authors also identified a gene co-methylation module related to the connection between a history of depression and inflammatory conditions as well as between TL and serum IL-6 levels." (PMID 36805537, 2023). "In the serum of patients with cardiovascular disease and depression, the levels of IL6 and CRP are higher than those of normal people, and more critically, IL6 and CRP can link the brain and heart through blood circulation." (PMID 38084332, 2023). "Patients with depression were also found to have lower IL-10 levels and an increased IL-6/IL-10 ratio in comparison with healthy individuals, which suggests disturbances in the regulation of cytokine secretion in depression." (PMID 37840785, 2023). "For example, high concentration of proinflammatory cytokines TNF‐alpha and IL‐6 were found in patients with major depression and clinical trials have indicated beneficial effects of anti‐inflammatory medications on major depression symptoms." (PMID 36573693, 2023). "It has been suggested that pro-inflammatory cytokines (e.g., tumor necrosis factor, interleukin (IL)-1, IL-6, and IL-18) participate in the pathogenesis of RA and the development of depression in patients with RA." (PMID 36835939, 2023). "We assessed depression and anhedonia and collected plasma IL-6 levels at baseline, 1 month, and 2 months after baseline." (PMID 37304432, 2023). "Cytokines such as IL-6 and TNF-α are known to be involved in IFN-α-induced depression and high levels of these cytokines is associated with increased risk of major depressive disorder." (PMID 36911685, 2023). "Regression analysis showed that a preoperative serum IL-6 level > 1.985 pg/mL was significantly correlated with severe depression status in patients with ENS (odds ratio = 9.76, p = 0.020)." (PMID 37324195, 2023). "The results indicated that ENS patients with higher serum IL-6 levels tended to suffer from severe depression before surgical treatment." (PMID 37324195, 2023). "In major depressive disorders with melancholic features, a positive correlation has been found between the severity of the disease and concentrations of cortisol and IL-6." (PMID 37108052, 2023). "The pro-inflammatory cytokines commonly associated with depression, tumor necrosis factor (TNF)-alpha, interleukin (IL)-1 and IL-6, and highly potent microbial antigens, lipopolysaccharides (LPS), possess the ability to cross the blood-brain barrier." (PMID 36986112, 2023). "In acute CHIKV infections, elevated levels of cytokines, including IL-6, are associated with stress susceptibility along with social factors that contribute to post-CHIKV depression." (PMID 38088664, 2023). "The concentrations of proinflammatory cytokines, like TNF-α, IL-1β and IL-6 were significantly higher in UC patients with symptoms of anxiety/depression." (PMID 36906523, 2023).
depression (continued). "On the other hand, fluoxetine treatment reversed depression and anxiety-like behavior and inhibited the activation of NF-κB and cytosolic IL-6 protein expression in CSIS rats." (PMID 37009097, 2023). "By clearance of pathogens and toxic cell debris, reactive microglia released a variety of inflammatory cytokines (IL-1β,IL-6,TNF-α), which caused chronic neuroinflammation and participated in the progression of depression." (PMID 37305539, 2023). "Accordingly, psychosocial stressors are likely to connect IL-6 secretion, amygdala emotional reactivity, and depression/anxiety through interacting with genetic factors." (PMID 37324818, 2023). "Specifically, IL-6 seems promising as a biomarker of depression state and recovery since its elevated level has been shown to decrease with successful antidepressant treatment." (PMID 34590201, 2023). "Psychological and physiological factors are related to anxiety, loneliness and depression, and increased levels of pro-inflammatory biomarkers (IL-6 and CRP) in patients that perceive themselves as isolated." (PMID 37510818, 2023). "TNF-α and IL-6 are inflammatory indicators and are strongly correlated with postoperative depression." (PMID 37598200, 2023). "On the other hand, another recent meta-analysis, which included 22 studies and a total of 20,791 participants, revealed a positive association between depression and CRP and IL-6 levels." (PMID 34590201, 2023). "Clinically, in comparison with healthy controls, patients with major depressive disorder have significantly higher levels of proinflammatory cytokines such as IL-6, TNFα, 8-OHdG, and F2-isoprostanes." (PMID 37599784, 2023). "Cytokines, which mediate the innate immune response, including IL-1, tumor necrosis factor (TNF)-alpha, C-reactive protein (CRP), and IL-6, from peripheral blood are considered the most reliable biomarkers of inflammation in patients with depression." (PMID 37065487, 2023). "The assessment of hypothalamic inflammatory responses induced by LPS stress involved the detection of the three inflammatory cytokines TNF-α, IL-1β, and IL-6 that play crucial roles in the pathogenesis of depression." (PMID 38062440, 2023). "TNF-α, IFN- α, IL-1, IL-1β and IL-6 are mostly found with increased concentrations in the serum of depression and anxiety patients." (PMID 37764111, 2023). "It is suggested that exercise can inhibit proinflammatory factors TNF-α, IL-6, and IL-18 to improve depression." (PMID 37239191, 2023). "As secondary goals, the use of analgesic medication, quality of life, depressive symptoms, and possible correlations between plasma levels of interleukin (IL)-1 beta, IL-6, and IL-10 as predictors of pain and depression were evaluated." (PMID 36944694, 2023). "Several meta-analyses have found positive correlations between blood levels of both CRP and IL6 with depression." (PMID 38299049, 2023). "A correlation was found between elevated IL-6 levels in mice, increased immobility in the forced swimming test, and decreased sucrose consumption as positive indicators of depression." (PMID 37687297, 2023). "Proinflammatory cytokines, involving TNFα, IL1β, IL6, and interferon, are important regulators in the pathogenesis of depressive disorder." (PMID 38273824, 2023). "The dependence between elevated interleukins IL-6 and IL-1 and depressive disorders has been described." (PMID 37240517, 2023). "A meta-analysis of various clinical trials in patients with depressive disorder shows a significant increase in the levels of IL-2, IL-6, TNF-α, IFN-γ compared to those in the control group." (PMID 37687297, 2023). "It is noteworthy that elevated serum IL-6 and TNF-α levels, as well as increased levels of salivary cortisol, are also associated with treatment-resistant depression." (PMID 37892186, 2023).